RBM5 (RNA binding motif protein 5)
Description:
Component of the spliceosome A complex. Binds to ssRNA containing the consensus sequence 5'-AGGUAA-3'. Regulates alternative splicing of a number of mRNAs. May modulate splice site pairing after recruitment of the U1 and U2 snRNPs to the 5' and 3' splice sites of the intron. May both positively and negatively regulate apoptosis by regulating the alternative splicing of several genes involved in this process, including FAS and CASP2/caspase-2. In the case of FAS, promotes exclusion of exon 6 thereby producing a soluble form of FAS that inhibits apoptosis. In the case of CASP2/caspase-2, promotes exclusion of exon 9 thereby producing a catalytically active form of CASP2/Caspase-2 that induces apoptosis.
Synonyms: H37; LUCA15; LUCA-15; G15; RMB5
Tractability: Small molecule: a structure with a bound ligand is known. PROTAC: ubiquitination databases record sites on it; its protein half-life has been measured.
Gene: Protein-coding gene on chromosome 3 (50,088,919 to 50,119,021, forward strand). Ensembl gene ENSG00000003756.
Subcellular location: Nucleus
Subcellular location (Human Protein Atlas): Nucleoplasm; End piece; Flagellar centriole; Mid piece; Perinuclear theca; Principal piece
Pathways (Reactome):
Metabolism of RNA: mRNA Polyadenylation; mRNA Splicing - Major Pathway
Disease: Dengue Virus-Host Interactions
Gene Ontology:
Molecular function: mRNA binding; protein binding; RNA binding; DNA binding; nucleic acid binding
Biological process: positive regulation of apoptotic process; regulation of alternative mRNA splicing, via spliceosome; spliceosomal complex assembly; negative regulation of cell population proliferation; RNA processing
Cellular component: nucleoplasm; nucleus; spliceosomal complex
Genetic constraint (gnomAD): Loss-of-function variants: 15 observed, 114.38 expected, observed/expected ratio (o/e) 0.13, 90% interval 0.087 to 0.2. The upper end of that interval is the gene's LOEUF score, 0.2, which puts it in group 1 of 6, group 1 being the genes least tolerant of losing a copy. Missense variants: 502 observed, 938.4 expected, observed/expected ratio (o/e) 0.53, 90% interval 0.5 to 0.58. Synonymous variants: 292 observed, 331.24 expected, observed/expected ratio (o/e) 0.88, 90% interval 0.8 to 0.97.
Homologues: Orthologues: macaque RBM5 (99% identical), dog RBM5 (99% identical), pig RBM5 (99% identical), chimpanzee RBM5 (99% identical), guinea pig RBM5 (98% identical), rat Rbm5 (98% identical), mouse Rbm5 (98% identical), rabbit RBM5 (98% identical), tropical clawed frog rbm5 (77% identical), zebrafish rbm5 (60% identical), Drosophila melanogaster CG4896 (33% identical), Drosophila melanogaster CG4887 (32% identical), and 1 more. Paralogues in human: RBM10 (55% identical), RBM6 (30% identical).
Diseases named in the same sentence as RBM5 in open-access papers:
RBM5 is named in the same sentence as 58 diseases in open-access papers, as found by Europe PMC text mining. Sharing a sentence is not in itself a finding about the gene and the disease. The quoted sentences say what the papers report.
lung carcinoma (33 papers, 2002 to 2024). "The RNA-binding protein RBM5 has been implicated as a tumor suppressor in multiple types of solid cancers, such as lung cancer." (PMID 38216972, 2024). "RBM5 levels (mostly found in the cytoplasm) have been linked to the progression of 75% of primary lung cancers, as well as prostate and some breast cancers." (PMID 36066672, 2022). "Rbm5 loss-of-function (heterozygous) mice exposed to the tobacco carcinogen 4-(methylnitrosamino)-1-(3-pyridyl)-1-butanone (NNK) develop more aggressive lung cancer." (PMID 34769392, 2021). "Our data provide in vivo evidence that reduced RBM5 function, as occurs in a large number of patients, coupled with exposure to tobacco carcinogens is a risk factor for an aggressive lung cancer phenotype." (PMID 29176597, 2017). "Upon exposure to NNK, Rbm5 loss-of-function mice developed lung cancer at similar rates to wild type mice." (PMID 29176597, 2017). "RNA binding motif 5 (RBM5) (also called Luca15 or H37), the tumor suppressor gene, maps to the human chromosomal locus 3p21.3, which is strongly associated with lung cancer." (PMID 26923134, 2016). "The RBM5 gene is a tumor suppressor gene (TSG) that is located within a 370 kb overlapping lung cancer allelic loss region on 3p21.3." (PMID 25441176, 2014). "RNA-binding motif protein 5 (RBM5) (also known as LUCA-15 or H37) maps to the human chromosomal locus 3p21.3, which is strongly associated with lung cancer." (PMID 25441176, 2014). "Of particular note, given published associations between RBM5 and human lung cancer, 9-month-old Rbm5sda/sda males and females had normal lung histology (data not shown)." (PMID 23935508, 2013). "RBM5 expression is down-regulated in primary lung cancer tissues and has been linked to poor prognosis." (PMID 23935508, 2013). "To further investigate the mechanism behind this modulation and sensitization process, we examined the expression of key apoptosis-associated genes in RBM5-overexpressing lung cancer cells." (PMID 22866867, 2012). "Interestingly, the earliest and most frequent genetic alteration associated with lung cancers involves a lesion in the region to which the RNA binding protein RBM5 maps." (PMID 28662214, 2017). "RBM5 has been implicated as a tumor suppressor gene in lung cancer and prostate cancer, but it is unclear whether RBM5 is a miR-483-5p target." (PMID 28727371, 2017). "However, actually RBM5 overexpression caused cell growth inhibition, indicating that in the lung cancer cells, RBM5-induced apoptosis overweighs RBM5-induced autophagy and induces apoptotic cell death." (PMID 26923134, 2016). "Several of these studies are designed to target RBM5, since deregulation of RBM5 and its downstream targets have been linked to tumorigenesis and tumor maintenance in a variety of cancers, including lung cancer, breast cancer, pancreatic cancer, prostate cancer, and vestibular schwannoma." (PMID 26923134, 2016). "The presentation of a mouse line with defective RBM5 with male sterility in isolation could be considered somewhat surprising given Rbm5's wide expression profile and data showing an association between RBM5 and human lung cancer." (PMID 23935508, 2013). "Moreover, RBM5 was evaluated as a therapeutic and diagnostic marker in lung cancer." (PMID 28061901, 2017). "Previous work reported that RBM5 is a tumor suppressor gene in lung cancer, and the gene locus antisense transcribed noncoding RNA, RBM5-AS1, is in contrast promoting tumorigenesis in breast and colon cancers." (PMID 38216972, 2024). "XIST-mediated sequestration of RBM5 mRNA leads to decreased protein expression levels, resulting in enhanced proliferation and survival of lung cancer cells." (PMID 39201688, 2024). "A notable example is the lncRNA XIST, which interacts with the mRNA of the tumor suppressor gene RBM5 (RNA Binding Motif Protein 5) in lung cancer cells." (PMID 39201688, 2024).
lung carcinoma (continued). "In 75% of primary lung cancers, as well as prostate and breast cancer, a possible reduction in RBM5 availability, mostly localized in the cytoplasm, has already been described." (PMID 36066672, 2022). "RBM5 (RNA-binding protein 5) has been confirmed as a tumor suppressor in different cancers, including lung cancer." (PMID 36193508, 2022). "The decrease of RBM5 expression can increase the invasiveness of lung cancer, that is, the increase of nodule number and tumor size." (PMID 33718153, 2021). "The gene of RBM5, also known as H37 or Luca15, located in chromosomal region 3p21.3, is frequently deleted in heavy smokers and lung cancer patients." (PMID 34769392, 2021). "For example, as regulators of alternative splicing of apoptotic genes, RBM5, RBM6 and RBM10 are frequently deleted or mutated in lung cancer." (PMID 34398362, 2021). "First of all, RBM5 is downregulated in about 75% of lung cancers as well as prostate and breast cancers." (PMID 32947864, 2020). "In contrast, both SCUBE3 and RBM5 genes show a lower expression level in group 1 of lung cancer samples than in group 2 of lung cancer samples and in normal samples." (PMID 31856825, 2019). "In a similar way, KRT18_SCUBE3 and KRT18_RBM5 were found as potential prognostic gene pairs for lung cancer." (PMID 31856825, 2019). "We also investigated the genes in the prognostic gene pairs KRT18_SCUBE3 and KRT18_RBM5 for lung cancer." (PMID 31856825, 2019). "It is important to note that this GLC20 SCLC cell line is a particularly appropriate model for aggressive SCLC, as RBM5 is downregulated in the majority of lung cancers." (PMID 28662214, 2017). "As tumourigenesis progressed, however, reduced Rbm5 expression lead to significantly more aggressive lung cancer i.e. increased adenocarcinoma nodule numbers and tumour size." (PMID 29176597, 2017). "Within this study, we have generated Rbm5 heterozygous knockout mice, i.e. analogous to the reduced expression seen in lung cancer patients, and have used them to demonstrate a role for RBM5 in in vivo tumour suppression function in the lung." (PMID 29176597, 2017). "In early research, RBM5 was reported to regulate the splicing of an apoptotic factor Fas and resensitize lung cancer cells A549 to cisplatin." (PMID 28061901, 2017). "In the present study, we found that autophagy induced by RBM5 overexpression in lung cancer cells acted a pro-survival way." (PMID 26923134, 2016). "Our previous studies demonstrated that RBM5 can inhibit the growth of lung cancer cells and enhance cancer cells’ sensitivity to cisplatin through apoptosis." (PMID 26923134, 2016). "The ectopic expression of RBM5 suppresses the growth of human lung cancer, breast cancer, fibrosarcoma, and hematopoietic cells." (PMID 26923134, 2016). "Our studies provide further data in vivo to explore the role and molecular mechanism of RBM5 in lung cancer pathogenesis and suggest a strategy for the development of rationally designed therapeutics using RBM5 as a target." (PMID 23721095, 2013). "There is increasing evidence suggesting that RBM5 plays an important role in lung cancer occurrence and development, nevertheless, there are few studies reporting on RBM5 expression in lung cancer tissues and tumor cell lines." (PMID 23721095, 2013). "In humans, RBM5 is one of 35 genes located within a 370 kb region on chromosome 3p21.3, which is frequently deleted in lung cancer." (PMID 23935508, 2013). "For the inhibitory effect of RBM5 on lung cancer, in current studies, it is reported that RBM5 modulates apoptosis by regulating the alternative splicing of apoptosis-associated pre-mRNAs, such as CASP2 and FAS/CD95." (PMID 23721095, 2013). "Currently, there is not an effective animal model for further in vivo exploration of the function and mechanism of RBM5 on primary lung cancer." (PMID 23721095, 2013).
lung carcinoma (continued). "The ectopic expression of RBM5 suppresses the growth of human lung cancer, breast cancer, renal tumors, fibrosarcoma, and hematopoietic cells." (PMID 23158838, 2012). "There is increasing evidence suggesting that RBM5 plays an important role in lung cancer occurrence and development; nevertheless, there are few studies reporting the RBM5 expression in lung cancer tissues and tumor cell lines." (PMID 22866867, 2012). "The result suggested that overexpression of RBM5 significantly increased apoptosis in lung cancer cells." (PMID 22866867, 2012). "In the preliminary study, our group validated that the expression of RBM5 is lower in human lung cancer tissues than normal tissues did, the overexpression of RBM5 inhibit the proliferation and induce the apoptosis of human lung cancer A549 cells." (PMID 23158838, 2012). "Two groups examined the RBM5 expression on a small number of lung cancer tissues and found that most lung cancer, except a large cell carcinoma subtype that showed higher RBM5 expression, had remarkably lower expression of RBM5." (PMID 22866867, 2012). "In the preliminary work, our group had found that human lung cancer tissues expressed less RBM5 than normal tissues did, and overexpression of RBM5 can inhibit the proliferation and induce the apoptosis of human lung cancer A549 cells." (PMID 23158838, 2012). "Previous studies have shown that RBM5 expression was frequently reduced in different cancers, including breast cancer, human schwannoma and 75 % of primary lung cancer specimens." (PMID 22537942, 2012). "In summary, our results showed that RBM5 significantly inhibits tumor growth and induces apoptosis of lung cancer cells by reducing the expression of Bcl-2, subsequently inducing the expression of cleaved caspase-3, cleaved caspase-9 and cleaved PARP." (PMID 22866867, 2012). "The candidate tumour-suppressor gene, LUCA-15/RBM5/H37, maps to the lung cancer tumour-suppressor locus 3p21.3." (PMID 17195868, 2006). "Previously, RBM5 was reported as a tumor suppressor gene in lung cancer." (PMID 38216972, 2024). "Due to their similarity and recent evidence that RBM10 mutates in up to 21% of lung cancer, majority of studies hypothesized that RBM10 has the tumor suppressive properties of RBM5 in small cell lung cancer." (PMID 33718153, 2021). "RBM5 can inhibit tumor cell growth in gastric cancer and lung cancer." (PMID 34804951, 2021). "RBM5 can inhibit the growth of lung cancer cells and induce apoptosis." (PMID 34804951, 2021). "RBM5 is a tumor suppressor gene in lung cancer and breast cancer, but its role in the pathogenesis of medulloblastoma (MB) remains unclear." (PMID 34804951, 2021). "In support of this hypothesis, in vitro over-expression of RBM5 was shown to inhibit the growth of human lung cancer cell lines by increasing apoptosis and inducing cell cycle arrest in G112." (PMID 29176597, 2017). "RBM5-enhanced autophagy acts in a cytoprotective way and inhibition of autophagy may improve the anti-tumor efficacy of RBM5 in lung cancer." (PMID 26923134, 2016). "Interestingly, mutation of a conserved tyrosine residue (corresponding to Tyr470 in RBM5, where it contributes to the recognition of the PRMs by the OCRE domain) is frequently found associated with lung carcinoma." (PMID 27894420, 2016). "Our previous study demonstrated that exogenous expression of RBM5 by the pcDNA3.1-RBM5 inhibited the cell growth of human prostate cancer and lung cancer in vivo and in vitro and resensitized the response of A549/DDP cells (cisplatin resistant counterparts of A549 cells) to cisplatin." (PMID 26923134, 2016). "Overall, these data indicated that RBM5 overexpression could induce autophagic flux in human lung cancer A549 cells, and this process could be suppressed by the autophagy inhibitor, 3-MA." (PMID 26923134, 2016).
lung carcinoma (continued). "However, when Beclin1-PI3K III complex was inhibited by 3-MA, Beclin1 expression was downregulated and autophagic flux was decreased, confirming a crucial role for Beclin1 in RBM5-induced autophagy in lung cancer cells." (PMID 26923134, 2016). "Our study demonstrated that EGFR expression is regulated by RBM5 in lung adenocarcinomas cells either in a direct or indirect way, which might be meaningful with regards to target therapy in lung cancer." (PMID 25441176, 2014). "In Oh’s study, they also reported that RBM5 could inhibit the growth of human lung cancer A549 cells in vitro and in vivo." (PMID 23721095, 2013). "At present, studies on the link of RBM5 and lung cancer are mainly confined to the cell lines." (PMID 22866867, 2012). "Taken together, in the light of all the observations, we suggest that RBM5 could be a promising candidate towards lung cancer clinical management in terms of the metastatic status." (PMID 22537942, 2012). "Despite increasing evidence showing the activity of the apoptotic modulator of RBM5 in lung cancer development, the detailed mechanism is still largely unknown." (PMID 22866867, 2012). "However, the role of RBM5 played in the occurrence and development of lung cancer is still not well understood." (PMID 22866867, 2012). "Our study demonstrates that RBM5 can inhibit the growth of lung cancer cells and induce apoptosis both in vitro and in vivo, which suggests that RBM5 might be used as a potential biomarker or target for lung cancer diagnosis and chemotherapy." (PMID 22866867, 2012). "Previous studies have shown that RBM5 mRNA and protein expression was frequently reduced in different cancers, including ras-transformed Rat-1 embryonic fibroblastic cells, breast cancer, human vestibular schwannoma, and primary lung cancer specimens." (PMID 23158838, 2012). "Few studies on the expression and function of RBM5 on lung cancer tissues, especially on the tissues of primary lung adenocarcinoma, could be found." (PMID 22866867, 2012). "Some studies have also shown that RBM5 could inhibit the metastasis and invasion of lung cancer." (PMID 34804951, 2021). "Therefore, a better understanding about regulation relationship of RBM5 on autophagy and the role autophagy plays in cell survival is critical for developing therapeutic strategies targeting RBM5 in lung cancer and understanding more about mechanisms of autophagy regulation." (PMID 26923134, 2016). "SFs, including QKI, RBM4, RBM5, RBM6, RBM10, and SRSF1, were involved in the development of lung cancer, as SFs play a regulatory role in splicing." (PMID 33047900, 2020). "The RBM5 (also known as H37 and LUCA-15) and RBM6 genes are located in a chromosomal region 3p21.3, which is frequently deleted in heavy smokers and lung cancers." (PMID 27894420, 2016). "Matrix protein deposition seems to be in addition regulated by a tumor suppressor gene, frequently lost in lung cancer, RBM5 (RNA-binding motif protein 5; chromosome 3p21.3)." (PMID 27018053, 2016). "Thus, modulating the sensitivity and regulatory mechanism of cells to RBM5 overexpression, such as through the use of 3-MA, could potentially serve as a strategy in sensitizing and reducing resistance of lung cancer cells to RBM5 targeting therapy by blocking RBM5-mediated protective autophagy." (PMID 26923134, 2016). "However, the relationship between RBM5 and autophagy in human lung cancer is still unknown." (PMID 26923134, 2016). "RBM5 and RBM10 were determined as a tumor suppressor in lung cancer progression." (PMID 39741300, 2024). "For example, RBM5 and RBM6 are frequently deleted in lung cancer and heavy smokers." (PMID 32947864, 2020). "The RNA binding protein, RBM5, resides within this region and is significantly downregulated, but not deleted, in the majority of lung cancers." (PMID 28662214, 2017).
lung carcinoma (continued). "The results of this study demonstrated that downregulation of activated EGFR, in the NCI-H1975 lung cancer cell line, did not, in fact, correlate with upregulation of RBM5, suggesting that RBM5 functions upstream of EGFR." (PMID 22537942, 2012). "The RNA-binding motif protein 5 (RBM5) was first discovered in lung cancer and was identified as a tumor suppressor because its coding region (3p21.3) is often absent in lung cancer." (PMID 38201567, 2023).